HCG18 (HLA complex group 18)
Synonyms: FLJ31598; FLJ25550; Em:AB014087.1; HCG17
Gene: Long non-coding RNA gene on chromosome 6 (30,223,522 to 30,327,401, reverse strand). Ensembl gene ENSG00000231074.
Diseases named in the same sentence as HCG18 in open-access papers:
HCG18 is named in the same sentence as 42 diseases in open-access papers, as found by Europe PMC text mining. Sharing a sentence is not in itself a finding about the gene and the disease. The quoted sentences say what the papers report.
gastric cancer (13 papers, 2020 to 2024). A primary or metastatic malignant neoplasm involving the stomach. "Accumulating evidence indicated that HCG18 is an oncogene in numerous tumors, including gastric cancer, clear cell renal cell carcinoma, and hepatocellular carcinoma." (PMID 34991445, 2022). "HCG18 expression is markedly enhanced in gastric cancer tissues, and knockdown of HCG18 suppresses the growth and metastasis of tumour cells." (PMID 34983361, 2022). "In previous studies, HCG18 was reported to facilitate the progression of gastric cancer, lung adenocarcinoma, and colorectal cancer and indicates poor prognosis of these malignancies." (PMID 35389764, 2022). "In this study, Long non-coding RNA, HCG18, promoted the proliferation, migration, and metastasis of gastric cancer cells in an HNF1A-dependent manner." (PMID 36499297, 2022). "HCG18 is overexpressed in gastric cancer and indirectly regulates Hippo signal transduction activity by inhibiting the expression of miR-141-3p." (PMID 34615480, 2021). "It was confirmed that silencing of HCG18 could inhibit gastric cancer progression via obstructing the activation of PI3K/Akt signaling." (PMID 35389764, 2022). "HCG18 promotes gastric cancer proliferation by adsorbing miR-141-3p and miR-197-3p." (PMID 34976998, 2021). "Although long non-coding RNAs (lncRNAs) have been demonstrated to be dysregulated in gastric cancer (GC), the function of lncRNA HCG18 (HCG18) in GC is elusive." (PMID 35240920, 2022). "The comparable regulatory network has also reported that miR-152-3p can negatively regulate DNAJB12, while lncRNA HCG18 can promote DNAJB12 by competitively binding to miR-152-3p, which enhances gastric cancer cells proliferation, migration, and invasion." (PMID 36499297, 2022). "In gastric cancer, HNF1A increased HCG18 expression and HCG18 promoted cancer progression through the miR-152-3p/DNAJB12 axis." (PMID 34991445, 2022). "HCG18 can increase the expression levels of WIPF1 and DNAJB12 and activate the PI3K/AKT axis in gastric cancer cells, thus promoting gastric cancer progression." (PMID 34976998, 2021). "Exosome-derived lncRNA HCG18 can up-regulate the expression of KLF4 and promote the polarization of M2 macrophages by sponging miR-875-3p in macrophages, thus regulating the progression of gastric cancer." (PMID 38627703, 2024). "In addition, lncRNA HLA complex group 18 (HCG18), regarded as an oncogene in various tumors, is also highly expressed in gastric cancer and accelerates tumor metastasis." (PMID 36986884, 2023). "It was also reported that miR-141 could be counteracted by long noncoding RNA (lncRNA) HCG18, therefore, the YAP/TAZ expression level was upregulated and promoted tumor cell migration and invasion in gastric cancer." (PMID 36624516, 2023). "Furthermore, a recent study demonstrated that HCG18 acts as a ceRNA for miR-152–3p, thereby derepressing its target gene DNAJB12 to promote the development of gastric cancer." (PMID 34983361, 2022).
bladder cancer (9 papers, 2020 to 2025). "LncRNA HLA complex group 18 (HCG18) was implicated in the progression of bladder cancer and glioma, but its role in GC is unknown." (PMID 32725768, 2020). "Further studies have identified HCG18 as downregulated in bladder cancer tissues and cell lines, suggesting its potential as a prognostic lncRNA." (PMID 40004558, 2025). "The role of lncRNA HCG18 was previously reported to be a cancer-promoting gene, related to bladder cancer, papillary thyroid cancer, etc.." (PMID 36854894, 2023). "The lncRNA HCG18 has been reported to regulate gene expression by acting as a ceRNA that sponges miR-34c-5p in intervertebral disc degeneration or miR-146a-5p in bladder cancer cells." (PMID 33203802, 2020). "The function of HCG18 in bladder cancer as a ceRNA is proven recently." (PMID 32725768, 2020). "lncRNA HCG18 can upregulate NOTCH1 by competitively binding to miR-34c-5p, thereby inhibiting bladder cancer." (PMID 40303288, 2025). "Another case is the lncRNA HCG18, possessing the most gain interactions, which could cooperate with NOTCH1 to regulate the proliferation and migration of bladder cancer cells." (PMID 34222227, 2021). "Among the lncRNAs, although HCG18 had not been selected, it was found that lncRNA HCG18 suppressed the bladder cancer progression by cooperating with NOTCH1 and miR-34c-5p." (PMID 32196072, 2020). "Moreover, it is reported that HCG18 suppresses cell PLF and MGT in bladder carcinoma via modulating miR‐34c‐5p/NOTCH1 axis." (PMID 32725768, 2020). "To date, there have been no reports on functions of SNHG14, HCG18, and MAGI2-AS3 in melanoma, but they constitute a precisely regulated ceRNA network in various solid tumors such as colon cancer, bladder cancer, liver cancer, etc., and regulate the malignant behavior of tumor cells." (PMID 33194692, 2020).
hepatocellular carcinoma (9 papers, 2020 to 2025). A malignant tumor that arises from hepatocytes. "It has been reported that HCG18 knockdown decreases cell proliferation, increases apoptosis, and enhances sorafenib resistance via activating ferroptosis in hepatocellular carcinoma; these effects are mediated via the HCG18/miR-450b-5p/GPX4 axis." (PMID 38778030, 2024). "A previous study has shown that HCG18 participates in vascular invasion of hepatocellular cancer by regulating immune cells." (PMID 34966747, 2021). "HCG18 is a key regulatory gene for vascular invasion in hepatocellular carcinoma, and high expression of HCG18 was found to have independent prognostic significance." (PMID 34527669, 2021). "The results of our study suggest that HCG18 should be a new target for treatment of hepatocellular carcinoma." (PMID 34527669, 2021). "Expression and survival analyses demonstrated that, among these predicted lncRNAs, SNHG1, HCG18, NUTM2A-AS1 and ASB16-AS1, and SNHG6 were markedly upregulated in hepatocellular carcinoma and linked to poor prognosis." (PMID 32257949, 2020). "HCG18 can contribute to hepatocellular carcinoma progression by increasing CENPM expression." (PMID 34976998, 2021). "Through performing expression and survival analysis of the lncRNAs in hepatocellular carcinoma, we found that five lncRNAs (LINC00662, HCG18, LINC00847, LINC01006, LINC01184) were confirmed as the key lncRNAs." (PMID 35627170, 2022).
lung adenocarcinoma (9 papers, 2021 to 2025). A carcinoma that arises from the lung and is characterized by the presence of malignant glandular epithelial cells. "It has been proposed that HCG18 accelerates lung adenocarcinoma development by targeting miR-34a-5p." (PMID 39089097, 2024). "In lung adenocarcinoma, HCG18 served as an oncogene and enhanced tumor progression by targeting the miR-34a-5p/HMMR axis." (PMID 34991445, 2022). "A previous study reported that the HCG18/miR-34a-5p/HMMR axis promoted the progression of lung adenocarcinoma." (PMID 35311097, 2022). "HCG18 can also act as an oncogene in lung adenocarcinoma by enhancing HMMR expression and can accelerate nasopharyngeal carcinoma progression by upregulating CCND1." (PMID 34976998, 2021). "HCG18 contributes to the progression of lung adenocarcinoma through the miR-34a-5p/HMMR axis." (PMID 34976998, 2021). "In addition, it can pass HCG18/miR-34a- The 5p/HMMR axis that can accelerate the progression of lung adenocarcinoma." (PMID 34323652, 2021). "HCG18/miR-34a-5p/HMMR axis were found could accelerate the progression of lung adenocarcinoma." (PMID 35830566, 2022). "However, HCG18 sponges Mir-34A-5p in LUAD to regulate HMMR expression, leading to the rapid development of lung adenocarcinoma and reduced clinical survival time in patients with lung cancer." (PMID 36447119, 2023).
intervertebral disc degeneration (5 papers, 2017 to 2022). "HCG18 is also involved in some nonneoplastic diseases, such as diabetic peripheral neuropathy, coronary atherosclerotic heart disease, vascular disease, and intervertebral disc degeneration, which means that HCG18 is an important pathogenic factor in human diseases and needs to be further studied." (PMID 34976998, 2021). "Our study was consistent with a previous report that HCG18 promotes intervertebral disc degeneration by sponging miR-146a-5p and regulating TRAF6 expression." (PMID 35240920, 2022). "It has been shown that HCG18 acts as a ceRNA of miR-146-5p and is up-regulated in intervertebral disc degeneration." (PMID 33203802, 2020). "Recent studies have discovered that HCG18 is highly expressed in intervertebral disc degeneration and promotes its development." (PMID 32725768, 2020).
osteosarcoma (5 papers, 2022 to 2025). A usually aggressive malignant bone-forming mesenchymal neoplasm, predominantly affecting adolescents and young adults. "In osteosarcoma, tumor cell invasion and migration were triggered by lncRNA HCG18 via the repression of miR-34a, a negative regulator of RUNX2, which increased RUNX2 levels." (PMID 37108164, 2023). "It was suggested that HCG18 has a critical role in regulating aerobic glycolysis by sponging miR-365a-3p to increase the expression of PGK1 in osteosarcoma cells." (PMID 37161350, 2023). "RUNX2 is involved in the long noncoding RNA HLA complex group 18 (LncRNA HCG18)-elicited tumorigenic phenotype in osteosarcoma." (PMID 37108164, 2023). "In addition, the novel lncRNA HCG18 enhances aerobic glycolysis in osteosarcoma cells via miR-365a-3p/PGK1 signaling pathway regulation, which accelerating the development of osteosarcoma cells." (PMID 36618348, 2022). "Overexpression of HCG18 promotes osteosarcoma cell proliferation by augmenting aerobic glycolysis through regulation of the miR-365a-3p/PGK1 axis, suggesting that HCG18 may serve as a promising therapeutic target for osteosarcoma intervention." (PMID 40303288, 2025).
colorectal cancer (4 papers, 2021 to 2025). A primary or metastatic malignant neoplasm that affects the colon or rectum. "Recently, HCG18 was classified as a cancer-related lncRNA and identified as significantly upregulated in colorectal cancer tissues and cell lines." (PMID 40004558, 2025). "The lncRNA HCG18 promoted the growth and invasion of colorectal cancer cells through sponging miR-1271 and upregulating MTDH." (PMID 36595551, 2023). "A previous study reported that lncRNA HCG18 could stimulate the progression of colorectal cancer cells through the WNT pathway." (PMID 35389764, 2022). "Long non-coding RNA human leukocyte antigen complex group-18 (HCG18) has been reported to promote cell proliferation and metastasis by binding with distinct microRNAs (miRNAs) or functional proteins in several malignancies, such as clear cell renal cell carcinoma and colorectal cancer." (PMID 35389764, 2022). "HCG18 could sponge with miR-1271, subsequentially activate MTDH/Wnt/β-catenin pathway, and ultimately fascinate the growth and invasion of colorectal cancer." (PMID 35389764, 2022).
liver cancer (4 papers, 2020 to 2025). An epithelial or non-epithelial malignant neoplasm that arises from the liver. "If we can further construct the "human liver cancer nude mouse subcutaneous transplantation tumor" model or HCG18 knockout mouse model on the basis of this model, the results of this study will be more convincing." (PMID 40303288, 2025). "Other study has demonstrated that lncRNA HCG18 promotes the proliferation and migration of liver cancer by hsa-miR-214-3p to regulate the expression of CENPM protein." (PMID 35590240, 2022). "Besides, HCG18 and THUMPD3-AS1 have been reported to function as oncogenes in some cancers, including liver cancer." (PMID 36339646, 2022).
lung carcinoma (4 papers, 2016 to 2023). "Compared with breast adjacent tissues, AFAP1-AS1, PVT1, HYMAI were downregulated in most breast cancer tissues, and lncRNA PVT1, BANCR, HCG18 were upregulated in lung cancer." (PMID 28938549, 2017). "Compared with adjacent tissues, PVT1, HCG18, EXOC3-AS1 were upregulated in most lung cancer tissues." (PMID 28938549, 2017).
nasopharyngeal carcinoma (4 papers, 2021 to 2022). A carcinoma arising from the nasopharyngeal epithelium. "LncRNA HCG18 participates as an oncogenic lncRNA in nasopharyngeal cancer (NPC) progression." (PMID 36359888, 2022).
breast carcinoma (3 papers, 2017 to 2022). "Moreover, knockdown of HIF-1α suppressed HCG18 expression in breast cancer cells." (PMID 36139678, 2022). "HCG18 by miR-103a-3p binding positively regulates the expression UBE2O (ubiquitin conjugating enzyme E2O) and thus activates the UBE2O/mTORC1 axis in breast cancer cells." (PMID 36139678, 2022). "There was a positive correlation between HCG18 and HIF-1α expression in breast cancer tissues." (PMID 36139678, 2022).
gastric adenocarcinoma (3 papers, 2021 to 2025). "HCG18 expression was increased in GC tissues than in adjacent normal tissues (p < 0.05) and significantly upregulated in human gastric adenocarcinoma cell lines (BSG823, HS-746 T, MKN-28, and 9811) compared with GSE-1 (p < 0.05)." (PMID 35240920, 2022).
glioma (3 papers, 2020 to 2021). A benign or malignant brain and spinal cord tumor that arises from glial cells (astrocytes, oligodendrocytes, ependymal cells). "As an immune-related gene, lnc-HCG18 plays an antitumor role in undifferentiated glioma." (PMID 33194692, 2020). "Among these, there were six lncRNAs (TTC28-AS1, AC090425.1, GUSBP11, LINC00092, HCG18, and FAM95B1) that have not been studied in gliomas, and we visualize the Kaplan–Meier analysis results (p < 0.05)." (PMID 34615480, 2021).
papillary thyroid cancer (3 papers, 2023 to 2024). "HCG18 is involved in the regulation of various physiological and pathological changes in papillary thyroid cancer, including cell proliferation, invasion, apoptosis, and epithelial-mesenchymal transition." (PMID 36602530, 2023).
cholangiocarcinoma (2 papers, 2023 to 2024). A carcinoma that arises from the intrahepatic biliary tree (intrahepatic cholangiocarcinoma) or from the junction, or adjacent to the junction, of the right and left hepatic ducts (hilar cholangiocarcinoma). "Initially, through bioinformatics tools, we observed abnormal expression of lncRNA HCG18 in cholangiocarcinoma." (PMID 36854894, 2023). "The lung metastasis model was conducted through tail vein injection, demonstrating that, the prevention of HCG18 expression suppressed the lung metastasis of cholangiocarcinoma as compared with si-NC group under fluorescence and HE staining." (PMID 36854894, 2023). "Through several functional experiments CCK-8, colony formation, EdU, transwell, flow cytometry, wound healing assays and animal study, we identified the biological function of HCG18 in cholangiocarcinoma." (PMID 36854894, 2023). "The following assays were determined to the influence of overexpression of HCG18 in cholangiocarcinoma." (PMID 36854894, 2023). "All the results declared that miR-424-5p was direct target of HCG18 with negative regulation and miR-424-5p was down-regulated both in cholangiocarcinoma tissues and cell lines." (PMID 36854894, 2023). "Through bioinformatics analysis in TCGA database to screen differential expressed lncRNAs, we found that higher HCG18 level in cholangiocarcinoma tumor tissue than in normal tissues." (PMID 36854894, 2023). "In conclusion, in this study, we firstly found a novel marker lncRNA HCG18 overexpression in cholangiocarcinoma." (PMID 36854894, 2023). "Here, we aimed to discover the biological activity of lncRNA HCG18 in cholangiocarcinoma, and the possible interaction between miR-424-5p and Sox9 influencing cancer cell growth and metastasis." (PMID 36854894, 2023). "Although we have fully demonstrated that HCG18 was potential marker for cholangiocarcinoma and contributed to tumor growth and metastasis through mediating miR-424-5p/SOX9 axis through PI3K/AKT pathway." (PMID 36854894, 2023). "Herein, a key primary conclusion of this study was that lncRNA HCG18 was up-regulated in cholangiocarcinoma tumor tissues and cancer cell lines compared to normal groups." (PMID 36854894, 2023). "This work aimed to discover the role of lncRNA HCG18 and its possible downstream mechanism in cholangiocarcinoma tumor progression." (PMID 36854894, 2023). "RIP assay showed the abundant enrichment of HCG18 and miR-424-5p in the precipitates of anti-Ago2, which indicated that HCG18 bound with miR-424-5p in cholangiocarcinoma cells." (PMID 36854894, 2023). "Taken together, lncRNA HCG18, served as a cancer-promoting gene, contributed to cholangiocarcinoma development and metastasis in vivo, which was consistent with the previous results in vitro." (PMID 36854894, 2023). "Exosome-derived lncRNA HCG18 could promote the growth and metastasis of cholangiocarcinoma cells through the miR-424-5p/SOX9 axis of the PI3K/AKT pathway." (PMID 38627703, 2024). "Additionally, qRT-PCR assay detected HCG18 expression level in four human cholangiocarcinoma cell lines (QBC939, HUCCT1, RBE, HCCC9810) and normal human intrahepatic bile duct epithelial cell line HiBEC." (PMID 36854894, 2023). "The result indicated that HCG18 was highly expressed in cholangiocarcinoma cell exosomes." (PMID 36854894, 2023). "Thus, we concluded that miR-424-5p played the suppressive role in cholangiocarcinoma development and the inhibition of miR-424-5p reversed the suppression of cancer cells induced by lncRNA HCG18 knockdown." (PMID 36854894, 2023). "From all above results, overexpression of lncRNA HCG18 could contribute to cholangiocarcinoma cancer cells proliferation, migration and invasion." (PMID 36854894, 2023). "Thus, cholangiocarcinoma cells transmit HCG18 to the surrounding cancer cells through exosomes." (PMID 36854894, 2023). "The role of HCG18 in cholangiocarcinoma still remains unknown." (PMID 36854894, 2023).
colon cancer (2 papers, 2020 to 2023). "HCG18 was overexpressed in colon cancer for increased proliferation that was reversed by HCG18 knockdown, which induced miR-1271-5p overexpression." (PMID 37190145, 2023). "HCG18 levels were proportional to the degree of colon cancer malignancy, and this relationship is thought to be due to sponging of miR-1271-5p." (PMID 37190145, 2023).
disc degeneration (2 papers, 2017 to 2018). "Xi et al43 demonstrated that the expression of HCG18 was up‐regulated in IDD patients and higher expression of HCG18 was correlated with the grade of disc degeneration." (PMID 30156374, 2018). "In addition, the expression of HCG18 was positively correlated with disc degeneration grade." (PMID 29038477, 2017). "In addition, HCG18 expression was up-regulated in the patients with IDD, bulging or herniated discs, and its level was positively correlated with the disc degeneration grade." (PMID 29038477, 2017). "HCG18 expression was positively correlated with the disc degeneration grade and the hernia size, suggesting that HCG18 might act as a promoter in the development of IDD." (PMID 29038477, 2017).
lymph node metastasis (2 papers, 2022). "This study showed that HCG18 expression was elevated in both HNSCC patient tissues and cell lines, and the expression of HCG18 was positively correlated with OS and lymph node metastasis, indicating that HNSCC patients with higher HCG18 expression levels had poorer clinical outcomes." (PMID 35389764, 2022). "Moreover, HCG18 was significantly high-regulated in EOC patients with lymph node metastasis compared to those without metastasis." (PMID 34983361, 2022).